AFP (alpha fetoprotein)
Diseases named in the same sentence as AFP in open-access papers (continued):
Sharing a sentence is not in itself a finding about the gene and the disease.
tumor (continued). "In our previous study, the immune response of AFP-specific T cells was found to be associated with tumor progression, whereas the immune response of SMNMS-specific T cells had a protective effect in patients with early onset HCC." (PMID 36618423, 2022). "Until now, several studies have reported that PNI was an independent predictive factor for survival and closely associated with AFP, tumor size and TNM stage in HCC patients who underwent resection." (PMID 35846958, 2022). "Patients with older age, larger tumor diameter, higher clinicopathologic staging, higher c-Met expression, and higher AFP levels were associated with a greater survival risk of fewer than 5 years." (PMID 35710379, 2022). "Other factors associated with RFS were AFP, ≥ 400 ng/mL (HR 2.96, 95% CI 1.04–8.39, p = 0.042) and imaging tumor thrombus (HR 4.69, 95% CI 1.44–15.28, p = 0.010)." (PMID 36464701, 2022). "Univariate and multivariate Cox regression analysis showed that sex, marriage, race, histological tumor grade, T stage, surgery, chemotherapy, AFP, and tumor size were independent risk factors for prognosis." (PMID 35296046, 2022). "A Spearman correlation analysis revealed that over-expression of tissue lncRNA-H19 and circulating miR-675 were significantly associated with old age, serum AFP level, large tumor size, and poor pathological grade." (PMID 36671388, 2022). "Higher AFP expression and lower tumor differentiation were shown to be associated with higher HCC invasiveness." (PMID 35875154, 2022). "An elevated AFP level was also related to a high risk of tumor recurrence after surgical resection and liver transplantation." (PMID 36358711, 2022). "Previous studies identified a number of factors associated with tumor recurrence, such as serum alpha-fetoprotein (AFP), microvascular invasion (MVI), pathological grade, venous invasion, and tumor size, but the results were inconsistent among the studies." (PMID 35875140, 2022). "Poor differentiation is associated with larger tumour size, upregulated AFP level, presence of MVI, and unfavourable prognosis in patients with HCC." (PMID 36100893, 2022). "Overall, radiological tumor progression and/or AFP progression during downstaging are associated with a significantly higher recurrence rate after LT in patients inside, as well as outside MC." (PMID 35529597, 2022). "The lower expression of RCL1 is associated with higher tumor stage, higher AFP level, vascular invasion, and poor prognosis." (PMID 35264160, 2022). "Numerous studies show that the early detection of HCC mainly relies on CTC evaluation, which is also associated with cancer staging, tumor metastasis, and the AFP level in the blood of patients." (PMID 35637960, 2022). "As a comparison, high AFP (>100 ng/mL) levels were associated with tumor size, vascular invasion, BCLC stages (p < 0.0001), and CRP (p = 0.0138)." (PMID 35053564, 2022). "retrospectively analyzed the association between TACE refractoriness and various biomarkers; they proposed that the main risk factors for refractory TACE include AFP, some liver function indicators and tumor imaging findings." (PMID 36212404, 2022). "Multivariable analysis identified neutrophil-to-lymphocyte ratio, alpha fetoprotein, tumor number, and tumor diameter as independent preoperative risk factors for recurrence." (PMID 33680963, 2021). "In our study, an elevated ALR was associated with portal vein invasion, AFP levels, tumor numbers, tumor sizes and MVI, and was an independent predictor for both DFS and OS." (PMID 34535132, 2021). "The combination parameter pair was also prognostically useful in the low-AFP patient subcohort and was associated with significant differences in patient tumor characteristics." (PMID 34540270, 2021). "The results showed that tumor diameter ≥ 10 cm and pretreatment AFP ≥ 200 ng/ml were associated with poorer OS." (PMID 34336647, 2021).
tumor (continued). "For HCC patients, the high expression of PD-L1 is associated with lower tumor differentiation, a higher level of AFP, more frequent vascular invasion, and worse prognosis." (PMID 34513678, 2021). "The results showed that age, sex, tumor number, tumor size, and AFP were independent risk factors for recurrence, while age, etiology, Child-Pugh class, tumor number, and γ-GT were independently associated with long-term survival." (PMID 34976804, 2021). "In the clinic, Serological markers is one of the diagnostic tools for HCC and alpha fetoprotein (AFP) is the main tumor biomarker available to guide the management of HCC." (PMID 34290977, 2021). "High AFP levels are associated with larger tumor, bilobar involvement, vascular invasion, poorly differentiated histology and decreased survival." (PMID 34006248, 2021). "Elevated serum AFP levels are associated with massive or infiltrative tumor type and portal vein tumor thrombus." (PMID 34885252, 2021). "Prognostic factors independently associated with OS were BCLC stage, CTP class, AFP, tumour size, presence of extrahepatic disease and geographical origin." (PMID 33071284, 2021). "Factors prognostic of OS in patients with HCC undergoing TACE include tumor size, tumor multiplicity, vascular invasion, extrahepatic spread, underlying liver functional reserve, α-fetoprotein (AFP) concentration, and performance status." (PMID 34204125, 2021). "An elevated NLR in patients with HCC is associated with highly malignant tumor characteristics, such as vascular invasion, presence of multiple tumors, and high AFP levels." (PMID 34677270, 2021). "In the present study, both multinodularity and elevated AFP level were tumor factors significantly associated with early recurrence." (PMID 33685409, 2021). "Further, its higher expression also exhibited association with higher tumor grade, metastasis, increased AFP levels, and poor patient prognosis." (PMID 34235179, 2021). "The base model (model 1) was then created by incorporating six variables (Edmondson–Steiner classification, clinical TNM stage, tumor size, tumor capsule, tumor margin, and AFP) determined to be associated with MVI both in logistic and LASSO analyses." (PMID 35096577, 2021). "We further investigated the differential prognosis between high and low expression levels of PNO1 in three high-risk relapse subgroups: tumor size ≥ 3 cm, high serum AFP level, and more positive rate of Ki-67." (PMID 34050137, 2021). "Subsequently, we found that clinical TNM stage, AFP, Edmondson–Steiner classification, tumor size, tumor capsule, tumor margin, tumor number, and ALT were risk factors for MVI formation based on the LASSO regression analysis." (PMID 35096577, 2021). "A previous study has reported that blood AFP level is still the independent risk factor for poor prognosis after adjusting for the presence of tumor enlargement." (PMID 34229698, 2021). "Using tumor-associated proteins with short half-lives, such as AFP and DCP, enables the post-treatment efficacy to be determined within two weeks." (PMID 33562238, 2021). "Of all the risk factors, race, AJCC stage, grade, tumor size, AFP, fibrosis score, radiotherapy, surgery and survival time were statistically different between the two groups." (PMID 34887446, 2021). "More advanced BCLC stages—characterized by gradual tumor growth along with an increase in nodule number, vascular invasion, and extrahepatic disease—are associated with high AFP levels." (PMID 34644732, 2021). "Higher SMAD4 promoter methylation is significantly associated with high tumor grade, recurrence, metastasis, and elevated AFP (p < 0.01)." (PMID 34571856, 2021). "High AFP values also correlated with an increased risk of drop-out from the waiting list for LT and an increased risk of tumour recurrence and reduced OS after LT." (PMID 34944957, 2021).
tumor (continued). "The clinical analysis of the paraffin-embedded tissues also revealed that the negative expression of Mapk10 was significantly associated with higher serum AFP, more tumor microsatellite nodules, advanced tumor stage, and the shorter OS of HCC patients." (PMID 33604188, 2021). "The LDH, α-fetoprotein (AFP), and ß human chorionic gonadotropin (ß-hCG) are included in the Germ Cell Carcinoma Collaborative Group’s risk stratification system as serum tumor markers with prognostic significance." (PMID 34778068, 2021). "The present study has investigated the most informative parameters influencing the diagnostic efficiency of tumor markers and the possibility of their combined use with AFP." (PMID 34513063, 2021). "in patients with HCC, circAKT3 was associated with tumor sizes, microinvasion, and higher AFP levels, suggesting its possible role in this disease." (PMID 33477833, 2021). "Multivariate Cox regression analysis demonstrated that decreased STAT5A expression, together with encapsulation, big tumor size, and high AFP level, was an independent factor associated with RFS and OS." (PMID 33155364, 2021). "As previously reported, blood AFP level is significantly associated with prognosis and early-relapse, and the multinodular tumor commonly develops from MVI in HCC patients, therefore, these two variables were further incorporated into the subsequent analysis." (PMID 34229698, 2021). "Former studies reported significant association of EpCAM expression in HCC with high tumor grade and AFP level." (PMID 35070966, 2021). "In BsAb therapy, while one antibody activates the effector T cell receptors such as CD3 and CD28, the other antibody causes a tumor-associated antigen, such as AFP, GPC3, and EpCAM, to initiate tumor cytotoxicity." (PMID 34696292, 2021). "On the other hand, high AFP levels are associated with a powerful tumor-host immune response and increased invasive and metastatic abilities of tumor cells, one of the reasons for the high recurrence rate of HCC after surgery." (PMID 35127471, 2021). "Pre-transplant serum AFP level has been frequently associated with tumor progression and recurrence and is an independent risk factor for patient survival after LT." (PMID 34203396, 2021). "AFP is a mammalian tumor-associated fetal glycoprotein, with molecular weight 68–72 kDa which depends on the species of origin." (PMID 34680245, 2021). "The clinicopathological correlation analysis showed that the negative expression of MAPK10 in HCC was significantly associated with higher serum AFP (p = 0.05), more microsatellite nodules (P = 0.025) and advanced tumor stage (P = 0.001)." (PMID 33604188, 2021). "DCP seems to be correlated with tumor size, with superior performance to AFP, and is also associated with a more aggressive phenotype." (PMID 33668839, 2021). "An age of >60 years, tumor size >5 cm, single nodular and AFP >300 ng/mL were associated with a longer RFS relative to others (P = 0.025, 0.019, 0.012 and 0.007 respectively)." (PMID 33995626, 2021). "This carcinoma is associated with a larger tumor volume, a higher serum alpha-fetoprotein, and a poor prognosis." (PMID 33566306, 2021). "Taken together, our data suggest an association between a decrease in AFP with tumour response and an increase in AFP level with disease progression." (PMID 33531690, 2021). "miR-21 ratio, miR-122, AFP, radiological response, number of nodules, tumor size, presence of CRPH, and BCLC stage were associated with PFS at the univariate analysis." (PMID 34440094, 2021). "PRMT4 expression was significantly associated with alpha-fetoprotein levels, tumor size, satellite nodules, and microvascular invasion." (PMID 34522186, 2021). "Other significant risk factors were tumors exceeding Milan criteria, AFP concentration > 200 ng/mL, micro and macrovascular invasion, and poor tumor differentiation." (PMID 34360995, 2021).
tumor (continued). "A high association between AFP progression and radiographic progression occurring within each tumour assessment period was observed (OR 5.1; 95% CI, 3.2–8.1; p < 0.0001 for up to week 6; OR 1.8; 95% CI, 1.2–2.8, p = 0.0065 for weeks 6–12)." (PMID 33531690, 2021). "Increasing AFP values are associated with lower survival and a higher tumor recurrence rate in patients at very early or early stages as well as poor prognosis in patients undergoing advanced HCC." (PMID 34389000, 2021). "Immunohistochemistry analyses have shown that RNF40 expression in tumor tissues is significantly higher than that in surrounding normal tissues and high levels of RNF40 are significantly associated with alpha-fetoprotein and tumor-node-metastasis tumor stage." (PMID 33199825, 2021). "Tumor antigens are commonly classified as tumor‐associated antigens (TAAs, such as alpha‐fetoprotein) and tumor‐specific antigens (TSAs, such as neoantigens)." (PMID 33942515, 2021). "In the univariate and multivariate analyses of risk factors for OS and RFS, the AFP level, the fulfillment of Milan criteria, tumor size, histologic grade, and microvascular invasion were identified as independent risk factors." (PMID 34065172, 2021). "Results showed that higher‐risk scores were significantly associated with higher AFP levels, higher histological grade, larger tumour diameter, vascular invasion and advanced clinical staging (TNM, BCLC and CLIP)." (PMID 33300278, 2021). "The secretion of AFP is associated with the aggressive biological behaviour of the tumour and correlates with vascular invasion and a low degree of differentiation of HCC." (PMID 34944957, 2021). "Here, we investigated the diagnostic accuracy of selected tumor biomarkers (i.e., AFP, PIVKA-II and GPC-3); adipokines (i.e., adiponectin and leptin) and IL-6, alone or in combination, for the discrimination between patients with or without NAFLD-related HCC." (PMID 34064999, 2021). "Nevertheless, we have shown the usefulness of AFP to predict early tumor response and the association of AEs in patients with a history of MTA treatments." (PMID 34439111, 2021). "In univariate analysis, HBV infection, high platelet count, large tumor size, beyond up-to-X criteria, and high alpha-fetoprotein (AFP) level were associated with acute ALBI-grade migration." (PMID 34503135, 2021). "Elevated levels of AFP have been associated with increased tumor size and portal vein thrombosis, as well as an increased risk of recurrence after liver transplantation." (PMID 34503144, 2021). "The peripheral blood Treg cell proportion in HCC patients was associated with tumor stage, AFP, PIVKA-II, tumor size, tumor encapsulation, vascular invasion." (PMID 33717135, 2021). "For OS, high aspartate aminotransferase (AST) level, large tumor size, high AFP level, and ALBI-grade migration to grade 3 were risk factors in univariate analysis." (PMID 34503135, 2021). "When associations of the risk score and clinicopathological characteristics were investigated, we found that the risk score was significantly related to advanced tumor and a higher level of serum AFP." (PMID 34970559, 2021). "The variables that showed a statistically significant difference in the univariate analysis were introduced in the multivariate analysis, and we found that only AFP > 400 ng/mL and tumor size > 5 cm were independent risk factors for poor OS." (PMID 34067711, 2021). "Elevated AFP is an important prognostic marker associated with the presence of microvascular invasion and poor tumor differentiation." (PMID 33754656, 2021). "AFP has been investigated for predictability of HCC recurrence because the elevation of AFP has been associated with tumor growth." (PMID 34065172, 2021).
tumor (continued). "Serum AFP, tumor size and vascular invasion are strongly associated with extrahepatic metastasis of HCC." (PMID 34680245, 2021). "High expression levels of OX40, as shown by immunohistochemistry and tumor genome atlas analysis, are associated with high serum alpha-fetoprotein level, vascular invasion and poor prognosis of HCC patients." (PMID 35127491, 2021). "We established a nomogram prediction model by combining these three risk factors with AFP level and tumor number." (PMID 34094938, 2021). "Alpha-fetoprotein (AFP) is the most commonly detected tumor-associated protein and is used for the early diagnosis of HCC." (PMID 34557478, 2021). "AFP level is a biomarker of HCC, and a high AFP level is a significant risk factor for tumor recurrence after curative treatment." (PMID 34503212, 2021). "While the level of tumour-infiltrating CD8 T+ cells in tumour tissues was negatively associated with serum AFP (p=0.019), tumor size (p=0.028), and lymphatic metastasis (p=0.039)." (PMID 34149929, 2021). "Other independent prognostic identified were CTP class, AFP, tumour size and underlying disease aetiology." (PMID 33071284, 2021). "For RFS, presence of ascites, tumor number ≥ 2, presence of microvascular invasion and microsatellite distribution of tumors, high Annexin A2 expression, AFP and AST > upper limit of normal were associated with RFS by univariate analysis." (PMID 34575275, 2021). "Previous studies have shown tumor size, tumor number, degree of tumor differentiation, AFP level, and surgical margins to be factors associated with postoperative recurrence." (PMID 33650288, 2021). "Increased risk of tumor recurrence was associated with maxim tumor size of ≥5 cm, presence of macro-vascular invasion, serum AFP ≥200 ng/ml and overexpression of PD-L1." (PMID 35117990, 2021). "Further, AMD1 expression was significantly associated with tumor size (p = 0.037) and preoperative serum alpha‐fetoprotein (AFP) level (p = 0.038)." (PMID 33783988, 2021). "They further suggested that MPVI was associated with multiple tumor nodules, larger tumor size and higher serum levels of both AFP and gamma-glutamyl transpeptidase (GGT)." (PMID 34123861, 2021). "It has been documented that preoperative blood AFP level, number of tumors, and diameter of tumor are risk factors for predicting prognosis of patients." (PMID 34229698, 2021). "High AFP level represents a more aggressive nature of the tumor and has been associated with a poor therapeutic outcome in patients with HCC; the results of the present study have confirmed this finding." (PMID 34733792, 2021). "A decline in serum AFP levels during treatment has been associated with tumour response in HCC patients who received various other systemic therapies." (PMID 33531690, 2021). "The univariable analysis revealed that DNMT1 expression was associated with tumour size and TB, AFP, and PD-L1 levels (P < 0.05)." (PMID 34589490, 2021). "HBV-HCC prognosis is linked to several factors, including the tumor size, alpha-fetoprotein (AFP), disease stage, and vascular invasion." (PMID 34272447, 2021). "Although univariate analysis showed that albumin, prothrombin time, alpha-fetoprotein level, Child-Pugh score, and lipiodol deposition in tumor were associated with OS, multivariate analysis showed that none of them was an independent prognostic factor for OS." (PMID 33738247, 2021). "Treatment is still ongoing and it is associated to a slow reduction of the tumor volume and of AFP levels." (PMID 33922938, 2021). "Multivariate analyses further revealed that increased miR‐23a expression, together with encapsulation, big tumor size, and high AFP level, was independent risk factors for OS and DFS." (PMID 33155364, 2021). "In the univariate analyses, tumor size, tumor number, subcapsular location, AFP, INR and sessions were found to be significantly associated with the presence of seeding after PTA in the training data set." (PMID 32702175, 2020).